CRYAB (crystallin alpha B)
Diseases named in the same sentence as CRYAB in open-access papers (continued):
Sharing a sentence is not in itself a finding about the gene and the disease.
cataract (16 papers, 2013 to 2024). Partial or complete opacity of the crystalline lens of one or both eyes that decreases visual acuity and eventually results in blindness. "Mutations in the alpha‐B‐crystallin (CRYAB) gene have initially been associated with myofibrillar myopathy, dilated cardiomyopathy and cataracts." (PMID 37772343, 2024). "Among the upregulated Mendelian cataract disease-associated genes were several crystallins (CRYAB and CRYBB2) and mitochondrial encoded genes (MT-ATP6, MT-ND1, and MT-CO2)." (PMID 35348588, 2022). "Mutations in the CRYAA and CRYAB crystallin genes are associated with autosomal dominant early onset human cataracts." (PMID 32833997, 2020). "The CRYAB gene encodes alpha-B crystallin protein, and mutations of CRYAB cause posterior polar cataracts, which is a distinct clinical type of cataracts." (PMID 33213085, 2020). "Surgical removal of cataracts is typically incomplete, and we estimate that this disease is associated with alpha-B crystallin (CRYAB) secreted from the retained lens material." (PMID 29850213, 2018). "Similarly, the arginine-120-to-glycine mutation is linked to early onset cataracts, a loss of chaperone function of the CRYAB protein, and myopathy." (PMID 32833997, 2020). "Mutations in the alpha‐B‐crystallin (CRYAB) gene have been associated with myofibrillar myopathy, dilated cardiomyopathy and cataracts." (PMID 37772343, 2024). "Module analysis and central network analysis revealed that αB-crystallin (CRYAB) may play an important role in the treatment of cataracts." (PMID 35860180, 2022). "In addition, alpha-B crystallin (CRYAB) may play a role in the incidence of cataracts and AMD by protecting cells from apoptosis, regulating cell signals and resisting oxidative stress." (PMID 29850213, 2018).
multiple sclerosis (14 papers, 2012 to 2025). A progressive autoimmune disorder affecting the central nervous system resulting in demyelination. "Crystallin alpha B (CRYAB) is a heat shock protein that exerts a protective role against multiple sclerosis in animal models." (PMID 40095747, 2025). "For example, in multiple sclerosis, CRYAB positive oligodendrocytes can come in contact with and activate microglia, whereas myelin debris removal by activated microglia is required for inducing remyelination." (PMID 36359800, 2022). "CRYAB (also known as alphaB-crystallin/HSPB5) is a small heat shock protein that has many protective functions including an immunomodulatory role in mouse models of multiple sclerosis, spinal cord injury, and stroke." (PMID 33761953, 2021). "For instance, anti-apoptotic and neuroprotective functions have been proposed for the α-Crystallin B (CRYAB) in the development of multiple sclerosis (MS)." (PMID 31729431, 2019). "CRYAB was initially identified as a negative regulator of T-cell responses in experimental autoimmune encephalomyelitis, whereas phosphorylation of intracellular CRYAB in astrocytes mediates reactive astrogliosis and worsens the pathology of multiple sclerosis in both the mouse and human brain." (PMID 36769067, 2023).
ovarian carcinoma (10 papers, 2016 to 2022). A malignant neoplasm originating from the surface ovarian epithelium. "High expression of CRYAB (HSPB5) was associated with significantly lower disease-free and overall survival for bladder, colon and ovarian carcinomas." (PMID 35311075, 2022).
colorectal cancer (9 papers, 2017 to 2025). A primary or metastatic malignant neoplasm that affects the colon or rectum. "The expression of the CRYAB gene has been identified as a prospective diagnostic indicator for a range of cancers, including prostate cancer, colorectal cancer, and gastric cancer." (PMID 38274814, 2023). "Among these, genes with positive coefficients (ABHD4, ABHD8, YJEFN3, CRYAB, and HSPA1A) were found to be risk factors, suggesting that their increased expression is associated with worse prognoses in colorectal cancer patients." (PMID 41293172, 2025). "As mentioned in Section 6.2, CryAB is a potential therapeutic target for some cancers such as osteosarcoma, gastric and colorectal cancer." (PMID 34831344, 2021). "Similarly, in colorectal cancer cell lines, CryAB expression is upregulated and promotes metastasis and invasion." (PMID 34831344, 2021). "Colorectal cancer (CRC) is one of the most prevalent cancers worldwide and Alpha B-crystallin (CRYAB) protein has been identified as a prognostic biomarker for CRC." (PMID 30082880, 2018). "Indeed, we observed that the correlation between MITF and CRYAB is also present in colorectal cancer, but not in breast nor lung cancer (data available in CANCERTOOL40)." (PMID 30310055, 2018).
lung carcinoma (9 papers, 2016 to 2025). "In addition, clinical data showed that CRYAB overexpression in lung cancer was associated with metastasis and a more malignant stage." (PMID 31097690, 2019). "M2 macrophages promote the invasion and metastasis of lung cancer through EMT by up-regulating the expression of CRYAB and activating the ERK1/2/Fra-1/slug signaling pathway." (PMID 34526059, 2021). "Overall, we demonstrated that M2 macrophages promote malignancy in lung cancer through the EMT by upregulating CRYAB expression and activating the ERK1/2/Fra-1/slug signaling pathway." (PMID 31097690, 2019). "Overall, this study showed that the conditioned medium from co-culture of M2 macrophages and cancer cells promotes cancer cell invasion through EMT and CRYAB upregulation, which in turn induces lung cancer metastasis in vivo." (PMID 31097690, 2019). "Utilizing the microfluidic chip and proteomic analysis to assess the lung cancer microenvironment, we focused on a specific protein, αB-Crystallin (CRYAB)." (PMID 31097690, 2019). "Here, we postulated that M2 macrophages, which are considered to be TAM-like, induce the malignancy potential of lung carcinoma cells by upregulating CRYAB, which results in EMT, via the ERK1/2/Fra-1/slug signaling pathway." (PMID 31097690, 2019). "The results showed that CRYAB upregulation promotes lung cancer metastases to the brain and liver, while down-regulating CRYAB dramatically decreased the metastatic ability, especially to the liver." (PMID 31097690, 2019). "CRYAB has been reported as a prognostic marker in several cancers, such as breast, renal, thyroid, nasopharyngeal, hepatocellular and lung cancers." (PMID 27105535, 2016). "However, CRYAB’s role in lung carcinoma, especially its relationship with the tumor microenvironment, remains poorly understood." (PMID 31097690, 2019). "Moreover, CRYAB upregulation in lung cancer cells by M2 macrophages also induced the ERK1/2/Fra-1/slug pathway, which is related to EMT and likely cell invasion." (PMID 31097690, 2019). "However, the roles of CRYAB and ERK1/2/Fra-1/slug signaling in the malignancy potential of lung cancer remain undefined, as well as the potential involvement of macrophages in this process." (PMID 31097690, 2019).
myofibrillar myopathy (9 papers, 2011 to 2024). "It has been shown earlier that mutations in CRYAB itself can cause myofibrillar myopathy and cardiomypathy." (PMID 37342207, 2023). "A homozygous disruption or genetic mutation of the bag3 gene causes progressive myofibrillar myopathy in mouse and human skeletal and cardiac muscle disorder while mutations in the small heat shock protein αB-crystallin gene (CRYAB) are reported to be responsible for myofibrillar myopathy." (PMID 21423662, 2011). "The ability of the supplement to enhance glutathione, as well as redox-sensitive chaperone proteins such as CRYAB, has applications for diseases such as myofibrillar myopathy (MFM)." (PMID 34829610, 2021). "Due to inconsistencies with reported myofibrillar myopathy (MFM), including autosomal dominant inheritance, late onset and a slowly progressive course, the severe, recessively inherited form of CRYAB (alpha‐B crystallin) gene‐related infantile MFM has been suggested." (PMID 31215171, 2019).
Parkinson disease (9 papers, 2012 to 2025). A progressive degenerative disorder of the central nervous system characterized by loss of dopamine producing neurons in the substantia nigra and the presence of Lewy bodies in the substantia nigra and locus coeruleus. "In neurodegenerative conditions, such as Alzheimer’s disease and Parkinson’s disease, aberrant expression of CRYAB has been associated with neuronal apoptosis (cell death) and the progression of neurodegeneration." (PMID 38274814, 2023). "Moreover, it has been observed that the CRYAB gene also exerts an influence on other neurodegenerative disorders, including Alzheimer’s disease and Parkinson’s disease." (PMID 38274814, 2023).
cardiac hypertrophy (8 papers, 2009 to 2025). "One good example is the small heat shock protein alphaB‐crystallin (CryAB) whose missense mutation (CryABR120G) causes aberrant Desmin and CryAB aggregation and results in cardiac hypertrophy." (PMID 35845350, 2022). "A missense mutation of CryAB showed UPS impairment prior to heart hypertrophy and was associated with delivery of ubiquitinated proteins into the 20S proteasome." (PMID 36111332, 2022). "CRYAB, the most abundantly expressed stress protein in the heart, has been demonstrated to play a vital role by interaction with ER stress and the mitochondrial apoptotic pathway during cardiac hypertrophy and myocardial infarction." (PMID 29867551, 2018). "At this very early stage of the disease and also the young age of the animals, intracellular CryAB aberrant aggregates are clearly detectable but cardiac hypertrophy and malfunction are not apparent yet in the R120G mice." (PMID 31297061, 2019).
prostate carcinoma (8 papers, 2018 to 2023). A carcinoma that arises from epithelial cells of the prostate gland. "miR-215-5p, for example, inhibits prostate cancer metastasis by targeting PGK1, whereas miR-671-5p increases prostate cancer metastasis by targeting the NFIA/CRYAB axis." (PMID 36884182, 2023). "So far, the CRYAB gene has been shown to suppress tumorigenesis only in prostate cancer and nasopharyngeal carcinoma (NPC)." (PMID 36713654, 2022). "This evidence was supported by the enhanced prognostic potential of a signature based on the concomitant alteration of MITF and CRYAB in prostate cancer patients." (PMID 30310055, 2018).
Alzheimer disease (7 papers, 2016 to 2024). A progressive, neurodegenerative disease characterized by loss of function and death of nerve cells in several areas of the brain leading to loss of cognitive function such as memory and language. "Oligos5 highly expresses CRYAB, a small heat shock protein, which is implicated in various protein aggregation-related neurodegenerative diseases, such as PD, Alzheimer’s disease (AD), amyotrophic lateral sclerosis (ALS) and prion disorders." (PMID 38245794, 2024). "CRYAB is implicated in various protein aggregation-related neurodegenerative diseases such as Alzheimer’s disease (AD), PD, ALS, tauopathies, Alexander’s disease, and prion disorders." (PMID 30675347, 2019). "Earlier, we have shown that in the cerebral cortex of OXYS rats, the development of signs of Alzheimer’s disease proceeds during an increase in p38 MAPK-dependent CryaB phosphorylation (p-s59-CryaB) without increasing expression of the gene encoding CryaB." (PMID 32731533, 2020). "CRYAB and HSPH1 are both chaperone proteins that prevent aggregation of mutant proteins and defects in CRYAB have been associated with Huntington’s disease and Alzheimer’s disease, where its levels decrease in age-dependent manner." (PMID 31260448, 2019).
glioblastoma (7 papers, 2007 to 2023). The most malignant astrocytic tumor (WHO grade IV). "Aberrant expression of CRYAB is associated with invasive behavior in various tumors, including glioblastoma." (PMID 38274814, 2023). "Abnormal expression of the CRYAB gene has become a focus in studying the mechanisms underlying glioblastoma development." (PMID 38274814, 2023). "In conclusion, our study has established a reliable diagnostic and prognostic model for glioblastoma and provided evidence for the upregulation of CRYAB and its promotion of tumor cell behavior in glioblastomas." (PMID 38274814, 2023). "The upregulation of CRYAB in glioblastomas suggests its potential role in promoting tumor occurrence and progression, which is consistent with previous research on CRYAB in other cancers." (PMID 38274814, 2023). "In particular, CRYAB plays a crucial role in the management of glioblastomas, a type of brain tumor." (PMID 38274814, 2023). "Our study represents the pioneering investigation examining the precise involvement of CRYAB in glioblastomas." (PMID 38274814, 2023). "Regarding cell cycle regulation, CRYAB has also been found to regulate the cell cycle of glioblastoma cells." (PMID 38274814, 2023). "Although the specific functions and interaction mechanisms of CRYAB in glioblastoma are not fully understood, it is considered to be one of the important factors involved in glioblastoma occurrence and development." (PMID 38274814, 2023). "A comparison of SNP array data revealed that CRYAB is gained or amplified in many cancers such as B-Cell neoplasms, non-small cell lung cancer, glioblastoma, melanoma, colorectal, bladder, pancreatic, breast, endometrial, renal, thyroid cancer, and sarcoma." (PMID 36624493, 2023). "Further comprehensive investigations are pivotal for determining the precise involvement of CRYAB in glioblastoma and may yield promising therapeutic targets for novel treatment approaches." (PMID 38274814, 2023). "However, the specific role and mechanisms of CRYAB in glioblastoma are still unclear." (PMID 38274814, 2023). "Targeting CRYAB may be a promising therapeutic strategy for glioblastoma." (PMID 38274814, 2023). "Heat shock protein, crystallin alpha B (CRYAB) has also been described to be released from glioblastoma multiforme (GBM) derived-exosomes in response to exposure to pro-inflammatory cytokines IL-1β and TNF-α, to exert an anti-apoptotic activity." (PMID 31555295, 2019). "CRYAB gene expression was lower in tumors than that in normal tissues except for CHOL, glioblastoma multiforme (GBM), KIRC, KIRP, brain lower grade glioma (LGG), and pancreatic adenocarcinoma (PAAD)." (PMID 36713654, 2022).
osteosarcoma (7 papers, 2016 to 2023). A usually aggressive malignant bone-forming mesenchymal neoplasm, predominantly affecting adolescents and young adults. "CRYAB is also categorized as a marker for lower overall survival in cancers such as renal cell carcinoma, osteosarcoma, colorectal, hepatocellular carcinoma, gastric, ovarian, and non-small cell lung cancer." (PMID 36624493, 2023). "In clear cell and papillary type renal cell carcinoma and colorectal cancer, CRYAB is used as a marker for higher tumor stage and distant metastases, and in osteosarcoma, it is a marker for increased metastases and poor chemotherapy response." (PMID 36624493, 2023). "The overexpression of miR-491-5p has been shown to restore the chemosensitivity of osteosarcoma cells to CDDP and to directly target CRYAB encoding crystallin alpha B, a protein that inhibits apoptosis and contributes to intracellular architecture." (PMID 35337159, 2022). "Expression of both KLF4 and CRYAB was higher in osteosarcoma tissues compared to normal bone tissues." (PMID 36077137, 2022). "αB-crystallin (CRYAB) is a human small heat-shock protein (sHsp) that is involved in tumorigenesis in several types of cancer, including osteosarcoma." (PMID 36077137, 2022). "After that, we analyzed the correlation between KLF4 and CRYAB in human osteosarcoma tissues and found that among 40 patient tumor tissue tested, 29 patients showed high expression of both KLF4 and CRYAB." (PMID 27105535, 2016). "Recent study has shown that the expression level of CRYAB was increased in osteosarcoma tissues and elevated CRYAB promotes osteosarcoma cell metastasis." (PMID 27105535, 2016). "The elevated expression of CRYAB was detected in osteosarcoma tissues and cell lines." (PMID 36077137, 2022). "CryAB may play an oncogenic role in osteosarcoma, as the downregulation of CryAB decreased cancer cell proliferation." (PMID 34831344, 2021). "Hence, to investigate the molecular mechanism, we screened the KLF4 regulated genes in osteosarcoma using mRNA array and found that CRYAB was a candidate gene." (PMID 27105535, 2016). "Moreover, we found that KLF4 enhanced osteosarcoma cell proliferation and migration via upregulating CRYAB." (PMID 27105535, 2016). "Among 16 identified proteins, alpha-crystallin B chain (CRYAB) and ezrin (EZR1) were further validated using immunohistochemistry of tissue microarrays of paired osteosarcoma and normal tissues." (PMID 36077137, 2022). "The results confirmed the higher expression of CRYAB and EZR1 in osteosarcoma." (PMID 36077137, 2022).
heart failure (6 papers, 2018 to 2025). Inability of the heart to pump blood at an adequate rate to meet tissue metabolic requirements. "Our observation of CRYAB phosphorylation-induced condensatopathy after MI is the first, to our knowledge, to implicate a role for dysregulated condensates in a common etiology for heart failure." (PMID 39932799, 2025).
Stroke (6 papers, 2019 to 2023). Sudden impairment of blood flow to a part of the brain due to occlusion or rupture of an artery to the brain. "Indeed, augmentation of intact CryAB consistently confers neuroprotection against ischemia-induced neuronal injury, while CryAB deficiency leads to increased lesion size and diminished neurologic function after stroke." (PMID 33472658, 2021).
breast tumors (5 papers, 2012 to 2021). "The CRYAB gene, which has been shown to be highly expressed in basal-like breast tumors with poor prognoses, was the top overexpressed gene in CDC that differentiated it from UTUC14." (PMID 27484008, 2016). "In addition, some of the DEPs identified in these signaling pathways were also differentially expressed between the male and female breast tumors, such as the ones encoded by CES1, CRYAB, NSF, PRKDC and SERPIND1 genes." (PMID 33656060, 2021).
desminopathies (5 papers, 2018 to 2025). "Our data show that TANGO2 is required for CRYAB activity and intermediate filament structure as its loss leads to a desminopathy that is consistent with those identified in patients carrying desmin and CRYAB mutations." (PMID 40480980, 2025). "These cells also exhibited high levels of α-crystallin B chain (CRYAB), a stress-associated chaperone that stabilizes desmin (a DUX4c partner,) and thus maintains intermediate filament integrity; this chaperone is up-regulated in desminopathies as well." (PMID 29329560, 2018).